CD1C (CD1c molecule)
Diseases named in the same sentence as CD1C in open-access papers (continued):
Sharing a sentence is not in itself a finding about the gene and the disease.
tumor (continued). "Although combined application of pDCs and CD1c+ DCs did not have an added value in T cell activation, we investigated whether it has an effect on other immunological components that are essential for tumor eradication." (PMID 27853652, 2016). "did not report the direct effect of tumor cells on DC3 development, a comparison of primary blood DC3s with breast tumor infiltrating CD1c+CD14+ DCs revealed phenotypical and transcriptional alignment." (PMID 38242119, 2024). "In conclusion, we establish cDC2s and not monocytes as potential precursors of tumor-induced CD1c+CD14+ cells, and hence refer to CD1c+CD14− cells as cDC2s and CD1c+CD14+ cells as CD14+ cDC2s." (PMID 38242119, 2024). "Conversely, CD1c+ mDCs, cells with an inferior capacity to cross-present antigen to CD8+ T cells compared with CD141+ DCs, were increased in tumor tissue, but the differences were at the expense of non-pCR patients and PLN patients." (PMID 35562400, 2022). "Consistent with murine data, expression of HLA-DR, CD86, CD40 and PDL1 was significantly increased in CD141+ cDC1 DCs (equivalent to mouse XCR1+) and CD1c+ cDC2 DCs (equivalent to mouse CD11b+), but not in pDCs, both pre- and post-Flt3L, upon co-culture with NDV-preinfected tumor cells." (PMID 36418317, 2022). "However, in the trial with CD1c+ mDCs, PFS was longer in patients with tumor-specific T-cells compared to patients without tumor-specific T-cells." (PMID 30999964, 2019).
infection (48 papers, 2007 to 2025). The state of being infected such as from the introduction of a foreign agent such as serum, vaccine, antigenic substance or organism. "Human blood-derived CD1c+ mDCs are susceptible to infection with BCG, up-regulating CD40, CCR7, HLA-DR, CD86 and other maturation markers, as well as producing TNF-α and IL-6." (PMID 37475964, 2023). "It was shown that infection with Borrelia burgdorferi causes upregulation of CD1c on myeloid dendritic cells, but the ligands are yet to be determined." (PMID 28386696, 2017). "Absolute numbers of all three subsets of DCs decreased after the first week of infection resulting in a significant loss of CD1c+ mDCs, CD16+ mDCs and CD123+ pDCs." (PMID 25915601, 2015). "Altogether, we report here that absolute numbers of all three subsets of DCs studied decreased after the first week of infection resulting in a significant loss of CD1c+ mDCs, CD16+ mDCs and CD123+ pDCs." (PMID 25915601, 2015). "However, almost all pDCs expressed CD4 and CCR5, which seem to imply that the pDCs were more susceptible to SIVmac239 infection than CD1c+ mDCs." (PMID 22174949, 2011). "Here, we have investigated the role of BV‐associated bacteria in altering HIV‐1 uptake, infection, and transmission in two different DC subsets present in vaginal mucosal tissue, monocyte‐derived DCs (moDCs) recruited upon inflammation, and primary CD1c+ myeloid DCs present in steady‐state." (PMID 40071689, 2025). "The maturation status of the CD1c+ mDCs following infection was performed by assessing expression of maturation markers on the cell surface and cytokine secretion on the cell supernatants." (PMID 37475964, 2023). "Nonetheless, secretion of the anti-inflammatory cytokine IL-10 was also reduced after inhibition of glycolysis in human CD1c+ mDCs upon infection with BCG, like murine BMDCs stimulated with LPS." (PMID 37475964, 2023). "To further investigate the role of glycolysis in the effector function of CD1c+ mDCs in response to infection with BCG, we analyzed the cell surface expression levels of the costimulatory molecule CD40 and the chemokine receptor CCR7." (PMID 37475964, 2023). "Consistent with pre-patent infection, a significant increase in sputum CD14-CD16- cDCs, and a strong trend (p = 0.056) for an increase in CD1c+ cDC2s, the dominant subset of sputum CD14-CD16− cDCs, was associated with human patent infection." (PMID 37012228, 2023). "Analysis on DEGs of CD1C+ DC barely found any genes that were relevant to antigen presentation or responses to infection." (PMID 35013182, 2022). "We also observed a major increase in the proportion of CD1c+ dendritic cells in the BAL on day 10 post-infection, a time when Ag-specific T cells were abundant in the airways." (PMID 35271298, 2022). "In contrast, the expression of IFN-I increased significantly after CA16 infection of CD1c+ DCs, the viral load and viral titer decreased, and Th1 and regulatory T-cell (Treg)-related transcription factors and cell factor expression increased significantly." (PMID 36613612, 2022). "We finally demonstrated that sorted CD1c+ DCs enabled BKPyV trans-infection to permissive cells while being resistant to infection themselves." (PMID 33592065, 2021). "Forty hours post infection, 1.4% of classical monocytes and 0.4% of CD1c+ MDCs were infected by PUUV, whereas PUUV antigen was undetectable in cells that were either uninfected or exposed to UV-inactivated PUUV." (PMID 28640917, 2017). "Numbers of CD1c+ mDCs significantly increased by 3 weeks post-infection while numbers of CD16+ mDCs remained closer to pre-infection levels." (PMID 25915601, 2015). "Numbers of CD1c+ mDCs were amplified (median percent changes above 0) while numbers of CD16+ mDCs stayed close to pre-infection counts (median percent changes close to or below 0) suggesting different modulation of these mDC subsets." (PMID 25915601, 2015).
infection (continued). "In mice, CD11b+ DCs, which are the functional homologs of human CD1c+ DCs, had the highest infection rate." (PMID 25474532, 2014). "After infection, CD1c+ DCs expressed HLA-DR, CD40, and CD83 (top) and produced IL-6, TNF-α, and IL-1β but not IL-23, TGF-β, or IL-12p70 (F and data not shown)." (PMID 25071784, 2014). "Three skin DC subsets were susceptible to DENV-2 infection ex vivo: LCs and CD14+ DCs were infected most efficiently while CD1c+ cells showed a lower infection rate." (PMID 25474532, 2014). "Infection with live Mtb revealed a higher responsiveness of myeloid CD1c+ DCs compared to CD141hi DCs and pDCs." (PMID 25071784, 2014). "The infection kinetics were delayed for CD14+ DC and CD1c+ DCs but peaked to similar infection levels as LCs after 36 hrs." (PMID 25474532, 2014). "Before infection, the percentage of Annexin V positive CD1c+ mDCs (31.7±4.0%) was obviously higher than apoptotic pDCs (1.4±0.5%)." (PMID 22174949, 2011). "There were no statistical correlations between CD4 and CCR5 expression on CD1c+ mDCs and virus loads during infection." (PMID 22174949, 2011). "Subsequently, the mean fluorescence intensities (MFI) of CD4 and CCR5 expressed on both CD1c+ mDCs and pDCs were observed during the acute SIVmac239 infection." (PMID 22174949, 2011). "We examined whether the enhanced viral uptake led to enhanced infection of CD1c+ DCs after overnight bacterial stimulation and exposure to HIV‐1 for 3 days with and without AZT." (PMID 40071689, 2025). "However, in both pre-patent and patent human infection, a significant increase in pulmonary DCs, specifically CD1c+ cDC2s was observed." (PMID 37012228, 2023). "The difference was that the expression of IFN-I significantly decreased after EV-A71 infection of CD1c+ DCs, the viral load and viral titer increased, and the expression of Th2 and follicular helper T-cell (Tfh)-related transcription factors and cytokines increased significantly." (PMID 36613612, 2022). "When exposed to Hantaan virus (HTNV) that causes severe HFRS, we similarly observed that classical monocytes and CD1c+ MDCs were susceptible to infection in vitro, without the induction of cell death." (PMID 28640917, 2017). "Murine infection models indicate that monocyte-derived cells are important for the initiation of Th1 immunity, and indeed the proliferating T cells induced by CD1c+ monocytes were primarily T-bet+ Th1 cells." (PMID 27311059, 2016). "Absolute numbers of CD1c+ mDCs significantly decreased by 8 dpi (median: 4 cells/μL [range: 0.6–10.8]; P<0.01) and 12 dpi (median: 3.4 cells/μL [range: 1.2–6.4]; P<0.01) compared to pre-infection (median: 15.2 cells/μL [range: 11–30.6])." (PMID 25915601, 2015). "However, while CD123+ pDC numbers remained low throughout infection, the numbers of CD1c+ and CD16+ mDCs increased after 3 weeks of infection, with a significant higher increase in numbers of CD1c+ mDCs compared to CD16+ mDCs." (PMID 25915601, 2015). "An elegant study recently performed by Silvin and colleagues demonstrated that CD1c+ DC were permissive to enveloped viruses like HIV-1 or Flu inducing their death thus providing viral Ags to CD141+ DCs which were shown to be resistant to infection by these pathogens." (PMID 33592065, 2021). "In order to assess the possibility of altered virus distribution by NAbs, CD1c+ DCs were isolated from peripheral lymph nodes of unvaccinated, SIVmac239-challenged macaques before and after passive NAb immunization, and DC-associated SIV RNA levels were quantified at the initial stage of infection." (PMID 17579714, 2007). "Overall, these data suggest that CD1c+ DCs show similar levels of HIV‐1 uptake and infection and a similar HIV‐1 localisation compared with moDCs following P. timonensis exposure." (PMID 40071689, 2025). "Our results provide the first evidence that glycolysis plays divergent roles in the maturation and migration of human CD1c+ mDC exposed to BCG, segregating with infection status." (PMID 37475964, 2023).
infection (continued). "To understand the role of the glycolytic pathway in CD1c+ mDC function in response to BCG, we pretreated the cells with the glycolysis inhibitor 2-DG prior to infection." (PMID 37475964, 2023). "At day 10 post-infection, the myeloid cells in the BAL were dominated by a population of CD1c+ cDC2s (BAL myeloid sub population 4)." (PMID 35271298, 2022). "Within the myeloid APC population, we also analyzed the levels of infection in CD14+ monocytes and CD1c+ DCs, and we found a significant detection of infected cells in the population of CD14+ monocytes at 24 hpi." (PMID 34160241, 2021). "Quantitative analysis of HIV-1SF33-infected cells showed that hBD-2PTD and hBD-3PTD reduced the infection of CD4+ T lymphocytes, CD68+ macrophages, and CD1c+ DC by 20–70% compared with untreated tissues." (PMID 34696473, 2021). "We found a decrease in all three subsets in the first week of infection, and CD123+ pDCs remained depleted while the CD1c and CD16+ mDC numbers returned to normal levels within three weeks." (PMID 25915601, 2015). "To better evaluate differences in numbers of circulating CD1c+, CD16+ mDCs and CD123+ pDCs compared to pre-infection, we examined the percent change in absolute numbers over time." (PMID 25915601, 2015). "In this study, we have reported the detection of SIV RNA in CD1c+ mDCs, CD16+ mDCs and CD123+ pDCs as early as day 8 post-infection." (PMID 25915601, 2015). "The absolute numbers of CD1c+ and CD16+ mDCs, and CD123+ pDCs were longitudinally analyzed in SIV-infected CD8+ T cell depleted rhesus macaques throughout infection." (PMID 25915601, 2015). "In these experiments, the mean infection rates were 28.1% for CD14+ DCs, 39.5% for LCs and 12.5% for CD1c+ DCs." (PMID 25474532, 2014). "In contrast to BCG stimulation, low concentrations of IFN-α were detected in culture of pDCs with Mtb-infected CD1c+ DCs (MOI 5, 48 h post-infection) (blue diamonds, p < 0.05 compared to Mtb-infected CD1c+ DCs monocultures)." (PMID 25071784, 2014). "During the acute SIVmac239 infection, the percentage of CD80+ CD1c+ mDCs increased from 1.36±0.24% to the peak at day 10 (15.25±8.61%) and sustained a high percentage till day 19 (3.93±0.48%), and showed a significant increase at day 19 (P = 0.011)." (PMID 22174949, 2011). "While P. timonensis did not induce infection of moDCs or CD1c+ DCs, the bacteria greatly enhanced HIV‐1 transmission to target cells by CD1c+ DCs but not by moDCs." (PMID 40071689, 2025). "We did not observe productive infection of CD1c+ DCs after 3 days either in the presence or absence of P. timonensis." (PMID 40071689, 2025). "Furthermore, mucosal CD1c+ DCs found in the intestinal lamina propria respond to bacterial and viral TLR stimuli, and transmit HIV‐1, altogether suggesting P. timonensis could also affect HIV‐1 susceptibility in other tissues and be relevant for infection of the male population." (PMID 40071689, 2025). "P. timonensis‐enhanced uptake increased productive infection in CD4+ T cells, but did not increase infection in moDCs or CD1c+ DCs." (PMID 40071689, 2025). "We did find that there was a trend toward more CD1c+ myeloid dendritic cells (mDCs) that expressed DC-SIGN in the lymph nodes in S2 of AHI (P = 0.11), suggesting an increased potential for trans-infection of HIV-specific CD4+ T cells in S2 of AHI." (PMID 39932316, 2025). "Thus, the decline in the number of pDCs and CD1c+ mDCs in patients with KD and their immature phenotype and the increase in TIM-3 expression on CD4+ T cells suggested a deficiency in the defensive system of patients with KD and may account for a high infection rate in these patients." (PMID 35222381, 2022). "We also detected some levels of infection of CD1c+ DC populations in some subjects; however, we did not observe a significant statistical increase in the percentage of infected cells in this population when data from 5 independent donors were analyzed." (PMID 34160241, 2021).
infection (continued). "Therefore, we analyzed the patterns of activation of DCs, specifically CD1c+ DCs (myeloid lineage) and pDCs (lymphoid lineage) during ZIKV and DENV2 ex vivo infections of PBMCs." (PMID 34160241, 2021). "In summary, both classical monocytes and CD1c+ MDCs were susceptible to PUUV infection in vitro, but infection did not result in cell death." (PMID 28640917, 2017). "However, while CD123+ pDC numbers remained low in blood throughout infection, the numbers of CD1c+ and CD16+ mDCs increased after 3 weeks of infection, with a significant higher increase in numbers of CD1c+ mDCs compared to CD16+ mDCs." (PMID 25915601, 2015). "Thus it seems that CD1c+ mDCs and CD16+ mDCs tend to expand in blood three weeks post-infection with a higher mobilization of CD1c+ compared to CD16+ mDCs." (PMID 25915601, 2015). "Similar to CD8+ T cell depleted animals, the percent change in CD1c+ mDCs in SIV infected animals without CD8 depletion increased at 2 weeks post-infection (median at 14 dpi: +9%) and remained constant (median at 56dpi: +11%)." (PMID 25915601, 2015). "However, we observed that infection with BCG did not alter the glycolytic reserve of the CD1c+ mDCs." (PMID 37475964, 2023). "Similar to CD1c+ mDCs, absolute numbers of CD16+ mDCs significantly decreased at 8 dpi (median: 5.7 cells/μL [range: 0.3–24.7]; P<0.01) and 12 dpi (median = 6.1 cells/μL [range: 2.7–18.8]; P<0.05) compared to pre-infection (median: 34.6 cells/μL [range: 7.2–117.4])." (PMID 25915601, 2015). "In order to evaluate whether or not blood DCs were associated with SIV (SIV RNA) or active viral replication in vivo (SIV DNA), we obtained highly purified CD1c+ mDCs, CD16+ mDCs, and CD123+ pDCs pre-infection and days 8 (acute), 21 (post-acute) and 40 (late stage) after infection." (PMID 25915601, 2015). "At least for dermal DCs, expression of these two receptors could therefore explain the more efficient infection of CD14+ DCs compared to CD1c+ DCs and the absence of infection in CD141+ DCs." (PMID 25474532, 2014). "In contrast to CD14+ DCs, infection of CD1c+ DCs and LCs did not impair their capacity to induce allogeneic CD4+ T cell proliferation, showing that DENV-mediated inhibition of T cell proliferation was DC subset specific and not a direct generic effect of the virus either on DCs or T cells." (PMID 25474532, 2014). "However, the apoptosis of CD1c+ mDCs was not significantly alter during the acute phase of infection, despite the fact that there was a little increase on most of the days, when compared with the day before infection." (PMID 22174949, 2011). "It has been confirmed that an increased percentage of Annexin V+ pDCs is significant during acute SIVmac239 infection, when compared with that of pre-infection, while no significant change could be found in CD1c+ mDCs." (PMID 22174949, 2011). "Moreover, unlike other CD1 isoforms, CD1c lipid loading is independent of compartment acidification, a process that Mtb actively inhibits to evade phagocytic destruction, giving CD1c a potential advantage in infection settings." (PMID 40709176, 2025). "Alternatively, infection of CD14+ DCs could affect their capacity to induce regulatory CD4 T cells in the skin, a function that has been associated with CD14+ DCs and not with CD1c+ DCs." (PMID 25474532, 2014). "In contrast, maturation marker expression did not increase on either CD1c or BDCA3 cDCs or pDCs and levels of circulating pDCs and CD1c+ cDCs both decreased following infection with a dose of 1,800 iRBCs." (PMID 31900030, 2020). "Using samples of normal human skin we detected productive infection of CD14+ and CD1c+ DCs, LCs and dermal macrophages, which was independent of DC-SIGN expression." (PMID 25474532, 2014). "Increasing concentrations of IFN-β had a significant inhibitory effect on infection in CD14+ DCs, CD1c+ DCs and macrophages but not in LCs." (PMID 25474532, 2014).
infection (continued). "Together the results are consistent with P. falciparum infection having differential effects on distinct populations of circulating DCs, with in vivo iRBC stimulation during the initial infection activating CD16+ DCs and inhibiting circulating CD1c+ cDCs, while pDCs are not affected." (PMID 31900030, 2020). "For human CD141+ DCs, infection-induced up-regulation of IFN-β and STAT-1 gene expression was low compared to CD14+ DCs and CD1c+ DCs, which might also reflect the lack of infection of the cells at these time points." (PMID 25474532, 2014).